TAS2R41 (taste 2 receptor member 41)
Description:
Receptor that may play a role in the perception of bitterness and is gustducin-linked. May play a role in sensing the chemical composition of the gastrointestinal content. The activity of this receptor may stimulate alpha gustducin, mediate PLC-beta-2 activation and lead to the gating of TRPM5 (By similarity).
Synonyms: T2R41; T2R59
Tractability: Antibody: its Gene Ontology location is reachable by antibodies, with high confidence; UniProt predicts a signal peptide or a membrane-spanning region. PROTAC: a small molecule that binds it is known.
Target class: Membrane receptor; Taste receptor (taste family GPCR); Taste family G protein-coupled receptor
Gene: Protein-coding gene on chromosome 7 (143,477,873 to 143,478,796, forward strand). Ensembl gene ENSG00000221855.
Subcellular location: Membrane
Pathways (Reactome):
Signal Transduction: Class C/3 (Metabotropic glutamate/pheromone receptors); G alpha (i) signalling events
Sensory Perception: Sensory perception of sweet, bitter, and umami (glutamate) taste
Gene Ontology:
Molecular function: bitter taste receptor activity; protein binding; G protein-coupled receptor activity
Biological process: detection of chemical stimulus involved in sensory perception of bitter taste; G protein-coupled receptor signaling pathway; sensory perception of taste
Cellular component: membrane; plasma membrane
Genetic constraint (gnomAD): Loss-of-function variants: 33 observed, 26.07 expected, observed/expected ratio (o/e) 1.27, 90% interval 0.96 to 1.68. The upper end of that interval is the gene's LOEUF score, 1.68, which puts it in group 6 of 6, group 1 being the genes least tolerant of losing a copy. Missense variants: 319 observed, 376.67 expected, observed/expected ratio (o/e) 0.85, 90% interval 0.77 to 0.93. Synonymous variants: 151 observed, 160.48 expected, observed/expected ratio (o/e) 0.94, 90% interval 0.82 to 1.08.
Homologues: Orthologues: chimpanzee TAS2R41 (98% identical), macaque TAS2R41 (86% identical), pig TAS2R41 (70% identical), dog TAS2R41 (69% identical), rat Tas2r126 (69% identical), mouse Tas2r126 (68% identical), rabbit TAS2R41 (63% identical), guinea pig TAS2R41 (59% identical), tropical clawed frog tas2r7 (29% identical), tropical clawed frog t2r13 (29% identical), tropical clawed frog tas2r4 (27% identical), tropical clawed frog t2r10 (26% identical), and 10 more. Paralogues in human: TAS2R60 (39% identical), TAS2R16 (33% identical), TAS2R9 (31% identical), TAS2R3 (30% identical), TAS2R7 (30% identical), TAS2R39 (30% identical), TAS2R43 (29% identical), TAS2R8 (29% identical), TAS2R30 (28% identical), TAS2R4 (28% identical), TAS2R46 (28% identical), TAS2R50 (28% identical), and 11 more.
Diseases named in the same sentence as TAS2R41 in open-access papers:
TAS2R41 is named in the same sentence as 4 diseases in open-access papers, as found by Europe PMC text mining. Sharing a sentence is not in itself a finding about the gene and the disease. The quoted sentences say what the papers report.
Alzheimer disease (1 paper, 2024). A progressive, neurodegenerative disease characterized by loss of function and death of nerve cells in several areas of the brain leading to loss of cognitive function such as memory and language. "The identification of significant SNP-Gene associations across all 28 taste genes, particularly those leading to the down-regulation of TAS2R41 and TAS2R60, presents a notable link to Alzheimer's disease within the African American cohort studied." (PMID 39284855, 2024). "In both cases, the specific mechanisms by which TAS2R41 and TAS2R60 influence the expression or function of EPHB6 and ADGRB3 in the context of Alzheimer's disease remain to be fully elucidated." (PMID 39284855, 2024).
TAS2R41 also shares sentences with these, for which no sentence is quoted: Anosmia (1 paper); nicotine addiction (1); skin melanoma (1).